DAGLB (diacylglycerol lipase beta)
Description:
Lipase that catalyzes the hydrolysis of arachidonic acid (AA)-esterified diacylglycerols (DAGs) to produce the principal endocannabinoid, 2-arachidonoylglycerol (2-AG) which can be further cleaved by downstream enzymes to release arachidonic acid (AA) for cyclooxygenase (COX)-mediated eicosanoid production. Preferentially hydrolyzes DAGs at the sn-1 position in a calcium-dependent manner and has negligible activity against other lipids including monoacylglycerols and phospholipids. Plays a key role in the regulation of 2-AG and AA pools utilized by COX1/2 to generate lipid mediators of macrophage and microglia inflammatory responses. Also functions as a polyunsaturated fatty acids-specific triacylglycerol lipase in macrophages. Plays an important role to support the metabolic and signaling demands of macrophages (By similarity).
Synonyms: KCCR13L; DAGLBETA
Tractability: Small molecule: a high-quality ligand is known; it belongs to a druggable protein family. Antibody: UniProt places it where antibodies can reach, with high confidence; its Gene Ontology location is reachable by antibodies, with high confidence; UniProt predicts a signal peptide or a membrane-spanning region; the Human Protein Atlas places it where antibodies can reach. PROTAC: ubiquitination databases record sites on it; its protein half-life has been measured; a small molecule that binds it is known.
Target class: Enzyme; Hydrolase
Chemical probes: KT109 (high quality), ML294
Gene: Protein-coding gene on chromosome 7 (6,407,846 to 6,484,190, reverse strand). Ensembl gene ENSG00000164535.
Subcellular location: Cell membrane
Subcellular location (Human Protein Atlas): Plasma membrane; Nucleoplasm
Pathways (Reactome):
Hemostasis: Arachidonate production from DAG
Gene Ontology:
Molecular function: lipase activity; protein binding; monoacylglycerol lipase activity; triacylglycerol lipase activity; diacylglycerol lipase activity
Biological process: arachidonate metabolic process; diacylglycerol catabolic process; neurogenesis; positive regulation of triglyceride catabolic process; prostaglandin biosynthetic process; regulation of inflammatory response; icosanoid metabolic process; lipid metabolic process
Cellular component: lysosomal membrane; plasma membrane
Genetic constraint (gnomAD): Loss-of-function variants: 66 observed, 72.27 expected, observed/expected ratio (o/e) 0.91, 90% interval 0.75 to 1.12. The upper end of that interval is the gene's LOEUF score, 1.12, which puts it in group 4 of 6, group 1 being the genes least tolerant of losing a copy. Missense variants: 1,065 observed, 912.96 expected, observed/expected ratio (o/e) 1.17, 90% interval 1.11 to 1.23. Synonymous variants: 414 observed, 371.56 expected, observed/expected ratio (o/e) 1.11, 90% interval 1.03 to 1.21.
Homologues: Orthologues: macaque DAGLB (99% identical), guinea pig DAGLB (87% identical), dog DAGLB (86% identical), pig DAGLB (83% identical), mouse Daglb (79% identical), rat Daglb (78% identical), rabbit DAGLB (78% identical), tropical clawed frog daglb (60% identical), chimpanzee DAGLB (57% identical), zebrafish daglb (56% identical), Caenorhabditis elegans Y49E10.18 (10% identical), Caenorhabditis elegans C39B5.14 (9% identical), and 21 more. Paralogues in human: DAGLA (34% identical), GOLT1B (5% identical), GOLT1A (5% identical).
Diseases named in the same sentence as DAGLB in open-access papers:
DAGLB is named in the same sentence as 17 diseases in open-access papers, as found by Europe PMC text mining. Sharing a sentence is not in itself a finding about the gene and the disease. The quoted sentences say what the papers report.
Anxiety (4 papers, 2017 to 2020). Intense feelings of nervousness, tension, or panic often arise in response to interpersonal stresses. "Selective inhibition of DAGLα, but not DAGLβ, induced significant periorbital allodynia in a dose-dependent manner, accompanied with increased secondary behavioral measures of distress (i.e., head pressing) and photophobia, but not reduced movement or anxiety." (PMID 33584293, 2020).
Parkinsonism (3 papers, 2022 to 2024). Characteristic neurologic anomaly resulting from degeneration of dopamine-generating cells in the substantia nigra, a region of the midbrain, characterized clinically by shaking, rigidity, slowness of movement and difficulty with walking and gait. "In the present work, we identified four different Parkinsonism-causal loss-of-function mutations in DAGLB and showed that DAGLB is the dominant 2-AG synthase in nigral DANs." (PMID 35715418, 2022). "Here we linked multiple homozygous loss-of-function mutations in 2-AG synthase diacylglycerol lipase β (DAGLB) to an early onset autosomal recessive Parkinsonism." (PMID 35715418, 2022). "To support the involvement of eCB signaling in regulating nigral DAN activity and pathogenesis of Parkinsonism, here we provided genetic evidence to demonstrate that deficiency in 2-AG synthase DAGLB contributes to the etiopathogenesis of Parkinsonism." (PMID 35715418, 2022). "Here, the authors identified four loss-of-function mutations in dicylglycerol lipase β (DAGLB) from six patients with early onset Parkinsonism." (PMID 35715418, 2022). "The expression and functional significance of DAGLB in nigrostriatal DANs may help to explain why multiple loss-of-function variants in DAGLB have been associated with early-onset Parkinsonism." (PMID 41537098, 2024). "It is plausible to suggest that these Parkinsonism-associated DAGLB variants could lead to decreased 2-AG production by nigrostriatal DANs, providing a previously unrecognized pathogenic mechanism for the disease." (PMID 41537098, 2024). "How does the DAGLB-deficiency contribute to Parkinsonism and nigral DAN dysfunction?" (PMID 35715418, 2022). "Therefore, all four Parkinsonism-related mutations disrupt the formation or stability of DAGLB protein, suggesting that the impairment of DAGLB-mediated 2-AG signaling may contribute to the etiopathogenesis of Parkinsonism." (PMID 35715418, 2022). "The predominant presence of DAGLB in nigral DANs may explain why the loss-of-function mutations in DAGLB lead to DAN dysfunction and Parkinsonism." (PMID 35715418, 2022). "Therefore, we reveal a DAN-specific pathophysiological mechanism of DAGLB dysfunction in the pathogenesis of Parkinsonism and provide the rationale and preclinical evidence for the potential beneficial effects of 2-AG augmentation in alleviating Parkinsonism45." (PMID 35715418, 2022).
atherosclerosis (1 paper, 2015). A disease characterized by the build-up of fatty material and calcium deposition in the arterial wall resulting in partial or complete occlusion of the arterial lumen. "Therefore, the genetic and lifestyle factors that lead to atherosclerosis development may be counteracted by either increased biosynthesis (via increased DAGLβ activity) or reduced hydrolysis (via decreased MAGL and/or other hydrolytic enzyme activities) of 2-AG." (PMID 26702404, 2015).
bladder cancer (1 paper, 2020). "To better understand the role of ECs and NAEs in bladder cancer, we analyzed gene expression data from TGCA database regarding the metabolic pathway of the ECS, comprising the synthetic enzymes (PLCB1-4, PTPN22, ABHD4, GDE1, DAGLA, DAGLB, and NAPE-PLD) and the hydrolytic ones (FAAH, NAAA, and MGLL)." (PMID 32260109, 2020).
cervical cancer (1 paper, 2022). A primary or metastatic malignant neoplasm involving the cervix. "After multivariate Cox regression analysis, eight genes were identified as key predictors of HLA-G-driven DEGs in the prognostic risk model for predicting the overall survival of patients with cervical cancer, including CD46, LGALS9, PGM1, SPRY4, CACNB3, PLIN2, MSMO1, and DAGLB." (PMID 35924232, 2022).
epilepsy (1 paper, 2024). A brain disorder characterized by episodes of abnormally increased neuronal discharge resulting in transient episodes of sensory or motor neurological dysfunction, or psychic dysfunction. "Four diagnostic biomarkers (ALOX12B, CBS, CPT1C, and DAGLB) showed high accuracy for epilepsy diagnosis, with an AUC value of 0.9592." (PMID 38419709, 2024). "Our research identified potential DELMRGs (ALOX12B, CBS, CPT1C, and DAGLB) in epilepsy, which may provide new ideas for studying the pathogenesis of Epilepsy." (PMID 38419709, 2024). "Our research unveiled potential DELMRGs (ALOX12B, CBS, CPT1C and DAGLB) in TSE, which may provide new ideas for studying the psathogenesis of epilepsy." (PMID 38419709, 2024).
gastric tumors (1 paper, 2022). "SNPs of DAGLB have been correlated with increased DAGLB expression in stomach tissues and were also significantly elevated in gastric tumors compared to adjacent tissues, thus confirming the potential of DAGLB as a susceptibility gene for gastric cancer." (PMID 35589867, 2022).
Obesity (1 paper, 2021). Accumulation of substantial excess body fat. "Human studies evaluating associations between DAGLA (and possibly also DAGLB) variants and obesity may provide some additional insight into whether modulating 2-AG synthesis impacts obesity-related outcomes." (PMID 34959715, 2021). "A review of these data found no SNPs in FAAH, MGLL, or DAGLA/DAGLB that showed genome-wide significant association (p < 5 × 10−8) with obesity or related outcomes (no SNPs in CNR1 either)." (PMID 34959715, 2021).
prostate carcinoma (1 paper, 2020). A carcinoma that arises from epithelial cells of the prostate gland. "The pharmacological blockade of DAGLβ by KT109 showed lower levels of 2-AG, arachidonic acid, and prostaglandins in Neuro2A cells, mouse peritoneal macrophages, mouse liver, and human prostate cancer cells." (PMID 33584293, 2020).
Stroke (1 paper, 2024). Sudden impairment of blood flow to a part of the brain due to occlusion or rupture of an artery to the brain. "The percentage of HLA+ cells that were also FABP5+, DAGLB+, STARD13 or IAH1+ was similar for MS and stroke (NA)WM." (PMID 38396116, 2024). "On the protein level, microglia in the non-nodular (NA)WM rarely expressed FABP5, DAGLB, IAH1, or STARD13, and microglia nodules in MS compared to in stroke were more often FABP5+, DAGLB+, or STARD13+." (PMID 38396116, 2024).
cancer (3 papers, 2020 to 2022). A tumor composed of atypical neoplastic, often pleomorphic cells that invade other tissues. "In addition, 1 SNP was detected in KMT2C, a BC oncogene, and 9 others were detected in or near 10 genes (SERAC1, DAGLB, MACF1, NVL, FBXW4, FANK1, KCTD4, CAVIN1; ATP6V0A1 and ZBTB20-AS1) previously associated with non-BC cancers." (PMID 35589867, 2022).
tumor (1 paper, 2020). "The division of TGCA data into four groups, based on the tumor stage, allowed us to highlight the statistically significant variation in the expression of only one synthetic enzyme, the sn1-specific DAGLB, which increases with the progression of the tumor stage (from T2b to T3–T4)." (PMID 32260109, 2020).
DAGLB also shares sentences with these, for which no sentence is quoted: depression (2 papers); anxiety disorder (1); Photophobia (1); post-traumatic stress disorder (1); ulcerative colitis (1).